KRAS (KRas proto-oncogene, GTPase)
Diseases named in the same sentence as KRAS in open-access papers (continued):
Sharing a sentence is not in itself a finding about the gene and the disease.
colorectal cancer (continued). "Since KRAS G12C mutation is not the most frequent in colorectal cancers, unlike lung cancer, considerable interest is focused on other potential KRAS inhibitors, particularly KRAS G12D, which represents the most common KRAS mutation in colorectal cancer." (PMID 40141164, 2025). "Colorectal cancer (CRC) is a leading cause of cancer-related mortality worldwide with KRAS mutations present in nearly 45% of cases." (PMID 40864819, 2025). "More perplexing conclusions have been reached in colorectal cancer (CRC) regarding the relationship between KRAS mutations and PD-L1 expression, with findings spanning positive, negative, and unrelated statements." (PMID 40611261, 2025). "For example, this gene promotes tumor progression and inhibits the immunotherapeutic response in colorectal cancers with mutations of the KRAS gene." (PMID 40298644, 2025). "In this study, we chemically characterized a wild strawberry extract through high‐resolution mass spectrometry and evaluated its antioxidant properties on two human colorectal cancer cell lines: KRAS mutated SW480 cells and E705 cells." (PMID 40207736, 2025). "Increased levels of PDP1 in KRAS mutant colorectal cancer (CRC) cells and tissues are linked to a worse prognosis." (PMID 40746885, 2025). "KRAS mutations, though most frequently found in colorectal cancer, were also detected in other cancer types, including breast (p.G12D), liver (p.G12C and p.G13D), and lung cancer (p.G13C, p.G12V, p.G12D, and p.G12C)." (PMID 39748775, 2025). "The pleckstrin 2 gene (PLEK2) encodes a membrane‐bound phosphatidylinositol generated by phosphatidylinositol 3‐kinase; this gene is a canonical downstream effector of KRAS activation, and its overexpression has been associated with colorectal cancer." (PMID 40013338, 2025). "Tumor-promoting driver mutations in KRAS occur in approximately 20–25% of human tumors, including colorectal cancer (CRC) (50%) and pancreatic ductal adenocarcinoma (PDAC) (93%)." (PMID 40790272, 2025). "Studies have shown that BRAF mutations are found in roughly 10–15%, while KRAS mutations are found in about 30–40% of diagnosed colorectal cancer cases." (PMID 40722718, 2025). "Epidemiological-neural network studies indicated KRAS mutations leads 40 types of cancer, exclusively pancreatic and colorectal cancers, with diploid and missense mutations as primary factors." (PMID 40157967, 2025). "Cost effectiveness of treatment sotorasib with panitumumab compared to standard care in cases of treatment of refractory colorectal cancer with mutated KRAS G12C was evaluated in another study." (PMID 41301043, 2025). "Approximately 30–40% of colorectal cancer cases harbor KRAS mutations, which are associated with a poor prognosis and resistance to certain treatments, including anti-EGFR monoclonal antibodies (panitumumab and cetuximab)." (PMID 39941797, 2025). "For example, KRAS mutations in colorectal cancer correspond with higher FDG absorption on PET imaging and unique MRI morphologic characteristics." (PMID 40506947, 2025). "Concurrently, the presence of KRAS mutations in colorectal cancer patients suggests the potential benefit of targeted drugs." (PMID 40730881, 2025). "KRAS mutations are prevalent in a wide range of cancers, including pancreatic cancer (up to 90%), colorectal cancer (50%), and lung adenocarcinoma (30%)." (PMID 40333779, 2025). "In colorectal cancer, KRAS mutations are the most common (43%), followed by NRAS (9%) and HRAS (1%)." (PMID 40308511, 2025).
colorectal cancer (continued). "KRAS mutant colorectal cancer cells resistance to palbociclib was associated with increased expression and phosphorylation of cyclin inhibitor p27, mediated by kinase Src." (PMID 40699853, 2025). "KRAS is the most commonly mutated oncogene in human tumors, especially lung, pancreatic, and colorectal cancers." (PMID 40244134, 2025). "Three probes were designed for the detection of glioma-associated IDH1, colorectal cancer-associated KRAS, and SARS-CoV-2-associated E484A." (PMID 40650970, 2025). "In our results, the diagnostic performance of KRAS mutation for colorectal cancer was also significant." (PMID 40771811, 2025). "KRAS mutations in colorectal cancer lead to the sustained activation of critical downstream signaling pathways, including the MAPK/ERK and PI3K/AKT pathways." (PMID 39941797, 2025). "The exon 1 of KRAS in cats was identified to harbor mutations in 12/13 codons in 2/7 (29%) cases of feline colorectal cancer and 2/3 (67%) cases of feline pancreatic adenocarcinoma." (PMID 40711277, 2025). "Although RAS mutations are highly prevalent in colorectal cancer (approximately 40% KRAS and 4% NRAS), until recently, they were considered ”undruggable”." (PMID 40731762, 2025). "These developments permit the early and precise detection of KRAS mutations in colorectal cancer patients." (PMID 40771811, 2025). "The G12D mutation in KRAS is frequently observed in pancreatic cancer, colon adenocarcinoma, non-small cell lung cancer, and colorectal cancer." (PMID 40629481, 2025). "KRAS was selected due to its frequent colorectal cancer mutation, prevalence in patient plasma, and established role in cellular transformation." (PMID 40226589, 2025). "KRAS mutations are common in colorectal cancer (30%–50%) and are considered important molecular markers for predicting the efficacy of the anti-EGFR monoclonal antibodies, cetuximab, and panitumumab." (PMID 40421293, 2025). "Given that KRASG12D is the most frequent KRAS mutation in both pancreatic and colorectal cancers, we further extended our analysis to include KRASG12D-mutant pancreatic (PANC-1) and colorectal (LS174T) cell lines." (PMID 40885716, 2025). "Clinical findings have indicated that colorectal cancer carrying KRAS mutation generally exhibits a lesser response to KRAS G12C inhibitors compared with NSCLC." (PMID 40304209, 2025). "Recently, the Food and Drug Administration approved adagrasib plus cetuximab for previously treated patients with KRAS G12C-mutated colorectal cancer." (PMID 40740763, 2025). "Approximately 40% of colorectal cancer (CRC) cases are characterised by KRAS mutations, rendering them insensitive to most therapies." (PMID 41188521, 2025). "In this study, we explored the prognostic impacts of HIF-1α, LOX and ITGA5 expression in the tumor microenvironment and their relationship with KRAS/NRAS/BRAF mutation status in colorectal cancers." (PMID 39857068, 2025). "The clinical relevance of KRAS mutations in colorectal cancer has been established through several pivotal studies." (PMID 40575161, 2025). "KRAS mutation was infrequent in colorectal cancers with high miR-21 expression compared with those with low-level expression." (PMID 40693022, 2025). "Secondly, mutation status holds prognostic value, with certain KRAS mutants correlating with adverse outcomes; for instance, colorectal cancer patients harboring KRAS mutations typically exhibit a poorer prognosis than their wild-type counterparts." (PMID 41514544, 2025).
colorectal cancer (continued). "In this study, we extended our bead-coupled LDR assay from synthetic oligonucleotides to genomic DNA extracted from colorectal cancer cell lines, enabling reliable identification of clinically relevant KRAS codon 12 mutations." (PMID 41441185, 2025). "In colorectal carcinoma, resistance to cetuximab has been observed in patients harboring KRAS mutations, a subset of RAS mutations." (PMID 40243851, 2025). "To assess the translational efficacy of RLY01, we further employed a patient-derived xenograft (PDX) model of colorectal carcinoma harboring a G12V mutation in KRAS." (PMID 40091835, 2025). "In KRAS-mutated colorectal carcinoma, Cetuximab, an anti-EGFR antibody, leads to the depletion of Glutathione (GSH) when combined with β-Elemene by inducing the iron-dependent accumulation of reactive oxygen species." (PMID 41516092, 2025). "The presence of a KRAS G12V mutation in the context of colorectal carcinoma is common – KRAS is mutated in approximately 40% of CRCs, with codon 12 substitutions (especially G12D and G12V) being the most prevalent." (PMID 41310725, 2025). "Among RAS mutations, the most frequently found oncogenic driver is KRAS mutations, observed in almost 97.7% of pancreatic ductal adenocarcinoma, 44.7% of colorectal carcinoma, and 30.9% of lung carcinoma cases." (PMID 41516092, 2025). "Activating KRAS mutations are produced by single substitutions of amino acids, and the resulting mutant proteins are associated with variable tumours, such as colorectal carcinoma, pancreatic ductal carcinoma, lung adenocarcinoma, and cholangiocarcinoma." (PMID 39996841, 2025). "With this purpose, we recently reported that at molecular level HIPK2 physically participates to RAS/MAPK complex, cooperates with KRAS signaling, and associates with tumor progression in human colorectal cancers." (PMID 39342278, 2024). "Oncogenic KRAS mutations are prevalent in colorectal cancer (CRC) and are associated with poor prognosis and resistance to therapy." (PMID 38464238, 2024). "Increasing evidence shows that KRAS mutation is correlated with poor prognosis in numerous cancers, including colorectal cancer (CRC), breast cancer, and melanoma." (PMID 38481800, 2024). "Colorectal cancer displays the most diverse profile of KRAS mutants with 28% of CRCs harboring a G12D mutation, 20% of CRCs harboring a G12V mutation, and 16% of CRCs harboring a G13D mutation (CITE)." (PMID 38464238, 2024). "These mutations are frequently seen in colorectal cancer, whereas KRAS, PIK3CA, and APC mutations are rarely observed in prostate cancer." (PMID 39902031, 2024). "As an example, EGFR and KRAS mutations render targeted therapies ineffective in some colorectal cancer patients." (PMID 39697234, 2024). "Knocking out mutated KRAS using CRISPR has been shown to inhibit colorectal cancer cell proliferation, both in vitro and in vivo." (PMID 39696697, 2024). "In one of these studies, the association of the CT genotype of SNP rs8720 in KRAS with an increased risk of colorectal cancer was proven." (PMID 39867023, 2024). "Recent studies have shown that Lu/BCAM is involved in regulating the adhesion between KRAS-mutated colorectal cancer cells and endothelial cells." (PMID 39000374, 2024). "Pancreatic and colorectal cancers are often KRAS mutated and are incurable when tumor DNA or protein persists or recurs after curative intent therapy." (PMID 38195752, 2024). "For example, in colorectal cancer liver metastases, only one new routinely available prognostic factor has been identified over the past 15 years (KRAS mutational status)." (PMID 39711552, 2024). "We found high fractions of patients with pancreatic cancer, colorectal cancer and lung adenocarcinoma with actionable KRAS mutations (39–64% of all cases)." (PMID 38890488, 2024). "The highest levels of KRAS mutation have been observed in pancreatic carcinoma, colorectal cancer, and lung malignancies." (PMID 39184150, 2024).
colorectal cancer (continued). "KRAS mutations, present in approximately 40% of colorectal cancers, are associated with resistance to EGFR inhibitors, complicating treatment." (PMID 39221315, 2024). "Oncogenic KRAS driver mutations in lung and colorectal cancers are thought to play a key role in driving neutrophil phenotype within tumors, with clear upregulation of neutrophil chemotactic protein production from metastatic lesions." (PMID 38358352, 2024). "Knocking down KRAS reduces the absorption of amino acids by colorectal cancer cells, while overexpression of mutated KRAS increases the expression levels of AATs." (PMID 38459595, 2024). "Precisely, MEK inhibitors have been utilized for the treatment of BRAF-mutated melanoma, KRAS/BRAF-mutated colorectal cancer, hepatocellular carcinoma, low-grade serous ovarian cancer, biliary cancers, and metastatic non-small cell lung cancers." (PMID 39728071, 2024). "Studies showed that, compared with other KRAS‐mutated colorectal cancers, KRAS c.34G>T (p.G12C)‐mutated colorectal cancer was associated with male sex, distal colorectal localization, and distant metastases to the lung, liver, and brain." (PMID 39039804, 2024). "At present, NRAS/KRAS mutations are widely considered to be associated with poor prognosis in a variety of cancers, including colorectal cancer and serous ovarian cancer." (PMID 38510490, 2024). "In colorectal cancers, the prevalence of KRAS G12D, G12S, G12V, and G13D mutations was greater in Black patients." (PMID 38297963, 2024). "Lu/BCAM and laminin α5 were observed to be upregulated in both tumor cells and the cellular microenvironment of liver metastases in colorectal cancer patients with KRAS mutations." (PMID 39000374, 2024). "Lastly, NGS was shown to have higher sensitivity compared to ddPCR detecting KRAS mutations in liquid biopsy samples of patients with colorectal cancer." (PMID 38394252, 2024). "The second target is KRAS, frequently mutated in cancers and serving as a therapeutic targeting, such as lung cancer, colorectal cancer and pancreatic cancer." (PMID 38647154, 2024). "The KRAS gene pattern in most gastric and colorectal cancer tissues was that of a heterozygous mutation." (PMID 39673361, 2024). "This comprehensive review aims to decipher the interplay between KRAS signaling and colorectal cancer, exploring the underlying mechanisms driving tumorigenesis, metastasis, and therapeutic resistance." (PMID 39456549, 2024). "We observed significant differences in colorectal cancer‐specific mortality between KRAS‐wild‐type, KRAS c.34G>T (p.G12C)‐mutated, and other KRAS‐mutated patients in Kaplan–Meier analysis (log‐rank p = 0.0002)." (PMID 39039804, 2024). "Colorectal cancer (CRC) frequently involves mutations in the KRAS gene, impacting therapeutic strategies and prognosis." (PMID 38539256, 2024). "First, the number of KRAS c.34G>T (p.G12C)‐mutated cases was modest, as this mutation is present in only 3%–4% of colorectal cancer patients." (PMID 39039804, 2024). "Recently, HIPK2 has been shown to cooperate with KRAS signaling and associate with human colorectal cancer progression." (PMID 39342278, 2024). "Colorectal cancer (CRC) is a deadly disease in which KRAS mutations are prevalent and are associated with poor prognosis." (PMID 39456549, 2024). "The mitogen-activated protein kinase (MAPK) cascade (RAS/RAF/MEK/ERK) is one of the most dysregulated pathways in human cancers, and one common one is colorectal cancer with KRAS and BRAF mutations." (PMID 39046631, 2024). "KRAS mutations are implicated in 25–30% of all human cancers, about 19% of non-small cell lung cancers (NSCLCs), about 40% of colorectal cancers (CRCs), and about 73% of pancreatic ductal adenocarcinoma (PDAC) cases." (PMID 38668053, 2024).
colorectal cancer (continued). "Kirsten rat sarcoma viral oncogene homolog (KRAS) is the most frequently mutated oncogene in various types of human cancers such as pancreatic, lung, and colorectal cancer, with G12, G13, and Q61 being the most prevalent mutant codons observed." (PMID 39704172, 2024). "The 5‐year colorectal cancer‐specific survival probabilities were 81% in KRAS‐wild‐type patients, 66% in KRAS c.34G>T (p.G12C)‐mutated patients, and 71% in other KRAS‐mutated patients." (PMID 39039804, 2024). "Compared with other KRAS mutations, KRAS c.34G>T (p.G12C) mutation has been associated with worse survival in advanced colorectal cancer patients who received conventional chemotherapy." (PMID 39039804, 2024). "KRAS is a frequently mutated oncogene in numerous types of cancer, including non-small cell lung cancer, colorectal cancer and pancreatic ductal adenocarcinoma." (PMID 38476985, 2024). "Precisely, this signaling pathway is highly involved in the development of BRAF-mutated melanoma, KRAS/BRAF-mutated colorectal cancer, and metastatic non-small-cell lung cancers." (PMID 38254833, 2024). "Preliminary results from the trial included patients with KRAS G12D- or G12R-mutated pancreatic and colorectal cancer following surgery and chemotherapy, and demonstrated serum tumor biomarker reduction and notable immune responses in 80% of patients." (PMID 39337530, 2024). "Identification of mutations in KRAS in single CTCs associated with stage III patients with colorectal cancer and correlated with shorter disease-free survival." (PMID 40026568, 2024). "KRAS mutations occur in approximately 40% of colorectal cancers (CRCs) and are associated with a poor prognosis and resistance to therapy." (PMID 39061234, 2024). "Activating mutations in PI3K has been shown to enhance tumorigenicity in in vitro endothelial cell models and colorectal cancer cell lines, compared to KRAS mutations alone." (PMID 39372214, 2024). "Among HPV-positive colorectal cancer patients, 1.8% exhibited wild-type KRAS, 5.4% had heterozygous mutations, and 3.2% had homozygous mutations." (PMID 39673361, 2024). "Supporting this, analysis from the cancer genome atlas dataset revealed that KRAS mutations were present in 45.5% of right-sided and 40.3% of left-sided colorectal cancers, while BRAF mutations occurred in 24.2% and 2.1% of cases, respectively." (PMID 39628993, 2024). "Dietary iron has been shown to affect the expression of tumor specific genes (specifically adenomas polyposis coli or APC) and can induce KRAS (Kirsten rat sarcoma viral oncogene homolog) mutations, promoting the risk of colon and colorectal cancers." (PMID 39246326, 2024). "For example, certain mutations, such as HER2 amplification in breast cancer or KRAS mutations in colorectal cancer, help classify tumors into distinct subtypes, guiding treatment decisions and predicting prognosis." (PMID 39421870, 2024). "Firstly, the prevalence of KRAS-G12C mutations in pancreatic and colorectal cancers is suboptimal, underscoring the imperative for the discovery and validation of alternative targeted agents." (PMID 39252322, 2024). "Most prominently, KRAS is mutated in 90% of pancreatic cancers, 45% of colorectal cancer, and 30% of lung cancer cases." (PMID 39184150, 2024). "Some patients showed evidence of epigenetic silencing of the MGMT gene by promoter hypermethylation, which was connected to a higher frequency of activating mutations in KRAS, a proto-oncogene frequently mutated in colorectal cancer." (PMID 39218931, 2024).